CRP (C-reactive protein)
Diseases named in the same sentence as CRP in open-access papers (continued):
Sharing a sentence is not in itself a finding about the gene and the disease.
COVID-19 (continued). "The present meta-analysis evaluated the therapeutic efficacy of NAC on COVID-19 patients based on data on CRP, D-dimer, and ferritin, duration of hospital and ICU stays, and PaO2/FiO2 available in the included studies." (PMID 37534078, 2023). "Age, urea, uric acid, ferritin, IL6, LDH, and CRP-based predictive probability algorithm calculating COVID-19 severity was found to be highly predictive of ICU admission for COVID-19 patients." (PMID 36819455, 2023). "A meta-analysis of five randomized trials, including a total of 16,048 patients, found that colchicine decreased COVID-19 severity and decreased C-reactive protein (CRP), indicating its potent anti-inflammatory effect in the presence of spike protein." (PMID 38024037, 2023). "In conclusion, cystatin C and other inflammatory factors such as ferritin, LDH and CRP can help the physician predict the consequences of COVID-19." (PMID 37217858, 2023). "The MII index is the product of NLR and CRP, which have been considered biomarkers of lethal outcome in COVID-19." (PMID 36832234, 2023). "Recent studies have indicated that IL-6 and CRP can be used to assess COVID-19 disease progression and prognosis." (PMID 37894092, 2023). "In this line, some authors have already integrated LDH, together with NLR, D-dimer, CRP, and SaO2 in machine learning models in order to assess the mortality of severe COVID-19 patients." (PMID 36829793, 2023). "At the onset of COVID-19, C-reactive protein and lactate dehydrogenase levels were elevated in all patients." (PMID 37568341, 2023). "In line with our findings, the results of previous research indicate that COVID-19 patients experienced a significant rise in CRP levels, with an average range of 20–50 mg/l21,40." (PMID 37363445, 2023). "Underlying biological plausibility explaining these associations include anti-inflammatory markers, including IL-6, CRP, antioxidants, antithrombotic effects, and adhesion factors that are beneficial in COVID-19 prevention." (PMID 37748553, 2023). "As those differences were noted, it is important to mention that only deceased COVID-19 patients in use with both drug classes showed a positive correlation between the important inflammatory cytokine IL-16, CRP, and cardiac troponin." (PMID 38274462, 2023). "Melatonin, angiotensinogen (AGT), CRP, and ceramide acid (Cer) levels were upregulated in COVID-19 patients (log2 (FC) = 0.486, 1.191, 2.002, and 1.712; P < 0.05)." (PMID 37849973, 2023). "This research aimed to assess the intake of vitamin E and its relationship with lipid peroxidation markers and C-reactive protein levels in patients with flu symptoms and COVID-19 diagnosis." (PMID 39263681, 2023). "Regarding CRP, several studies have considered it as the most sensitive inflammatory marker for predicting the severity of COVID-19." (PMID 37510647, 2023). "During the stage of systemic inflammation in COVID-19, there is a significant increase in inflammatory biomarkers like IL-2, IL-6, and CRP, which are dramatically enhanced." (PMID 38106427, 2023). "In patients who died from COVID-19, the level of CRP was about 10 times higher than in those who recovered." (PMID 36975366, 2023). "Hs-CRP and Ferritin values were higher in patients with severe COVID-19 than patients with mild/moderate COVID-19 after COVID treatment." (PMID 36867280, 2023). "We prospectively analyzed levels of TRAIL, IP-10, CRP, and the BV score, in children with suspected COVID-19." (PMID 36757525, 2023). "Significant differences were registered between the form of COVID-19 depending on the vaccination status, between LDH concentrations depending on the virus variant, and in IL-6, CRP, and ferritin concentrations and vaccination status depending on the gender." (PMID 37239895, 2023).
COVID-19 (continued). "There are several strengths of the current study including the establishment of the relationship between use of anakinra or tocilizumab and different biochemical markers such as ferritin, LDH, D-dimer, and CRP in mild to moderate COVID-19 cases." (PMID 37046952, 2023). "Blood specimens were collected and indicate several laboratory features of severe COVID-19, such as increased C-reactive protein (CRP) and interleukin-6 (IL-6)." (PMID 37417740, 2023). "Similar results supporting this finding were conducted in a group of 12 COVID-19 patients and found that decreased HRV was associated with increased levels of inflammation, as measured by C-reactive protein (CRP) and interleukin-6 (IL-6) levels." (PMID 37629687, 2023). "The aim of the study was to investigate the serial changes in inflammatory indices derived from blood cell counts and C-reactive protein (CRP) levels in COVID-19 patients with good and poor outcomes." (PMID 36832234, 2023). "A considerable rise in ferritin, CRP, and lactate dehydrogenase indicates an inflammatory response in COVID-19 patients before antiviral therapy." (PMID 38024833, 2023). "These inflammasome derivatives are correlated with COVID-19 severity markers such as IL-6, CRP and LDH." (PMID 36961847, 2023). "Plus, elevated levels of CRP were found in up to 86% of severe COVID-19 cases in some studies, with levels typically ranging from 20 to 50 mg/l on average." (PMID 38051999, 2023). "As high CRP levels are along with COVID-19, lowering CRP levels by therapeutic apheresis potentially reduces the pathological progression in the early stage." (PMID 37674786, 2023). "We established a positive correlation (r=0.7 p<0.05) between the level of CRP and COVID-19 severity." (PMID 37545134, 2023). "Based on the six fitted models, hospitalized in ICU, respiratory distress, age, diabetes, CRP, PO2, WBC, AST, BUN, and NLR were associated significantly with predicting LOHS of COVID-19." (PMID 37415112, 2023). "In our patient population, the levels of CRP on admission to hospital in patients with COVID-19 were closely related to the severity of illness." (PMID 36744291, 2023). "A major modulator of the acute inflammatory response in ARDS and CRS, the pro-inflammatory cytokine IL-6 also appears to play a role in severe COVID-19 and contributes to increased C-reactive protein levels, hypercoagulation, and hyperferritinemia." (PMID 37649125, 2023). "Laboratory parameters reflecting organ dysfunction (creatinine, urea, LDH), inflammation (CRP, PCT) or COVID-19 associated coagulopathy (D-dimer)." (PMID 37744227, 2023). "A previous study also showed that ESR and CRP are biomarkers of inflammation and were significantly elevated in patients with COVID-19." (PMID 37390087, 2023). "As such, our findings indicate that the inflammatory processes during acute COVID-19 and the combination of later immune-inflammatory processes (CRP and KYN/TRY) and IR determine to a large extent the physio-affective phenome of Long COVID." (PMID 37333619, 2023). "Intravenous administration of NAC showed clinical upliftment in patients over 40 with COVID-19 on mechanical ventilation, mainly through significant reductions in inflammatory markers, ferritin, and CRP." (PMID 37534078, 2023). "Exclusively for RTEL1 mutated, NLR trends reflected ventilation treatments better than CRP, which is currently the most used prognostic biomarker for COVID-19." (PMID 37328761, 2023). "The CRP is an acute phase reactant which functions as a reliable biomarker and is recommended as a predictor of COVID-19 severity and mortality." (PMID 36855103, 2023). "Multiple linear regression of Ct value, age, BMI, D-dimer and CRP to predict SpO2 level in COVID-19 patients." (PMID 36999046, 2023). "A recent study revealed that COVID-19 patients have elevated levels of biomarkers such as CRP, LDH, and IL-6 in case of extreme cytokine storm syndrome." (PMID 36671484, 2023).
COVID-19 (continued). "Transcripts of genes encoding 6 biomarkers, IL-1β, IL-6, IL-10, C-reactive protein, IDO1 and ACE2, were measured by RT‒qPCR in saliva samples of patients and COVID-19-free individuals." (PMID 37715121, 2023). "The present study investigated the profile of three biomarkers during hospital admission of pregnant women—D-dimer, C-reactive protein (CRP), and ferritin—and their correlation with the severity and outcome of COVID-19." (PMID 37510647, 2023). "Laboratory parameters like elevated CRP and IL-6 predicted COVID-19 disease severity and the need for mechanical ventilation in COVID-19 patients." (PMID 38152668, 2023). "Persistently increased levels of NLR and CRP have been shown to be related to severity of imaging findings on chest computed tomography in hospitalized patients with COVID-19." (PMID 37391742, 2023). "Since previous studies reported that the CRP marker significantly correlated with the severity of COVID-19 as a predictor factor, we analyzed the relationship between TRIM56 mRNA level and CRP value in all patients included in this study." (PMID 38051999, 2023). "The univariate analysis of the main laboratory parameters revealed a significantly higher frequency of inflammatory syndrome (elevated C-reactive protein, procalcitonin, and ferritin) in the group of patients diagnosed with COVID-19." (PMID 37046564, 2023). "COVID-19 severity factors such as PaO2/FiO2 ratio, SO-FA score and CRP were correlated with certain apolipoproteins." (PMID 36902035, 2023). "FLR has prognostic value in COVID-19 patients, and appears unrelated to other inflammatory markers such as CRP and WCC." (PMID 37893192, 2023). "There is also a very strong correlation between the C-reactive protein and the severity of COVID-19 (rS = 0.9) (p = 0.02)." (PMID 37390087, 2023). "In our patients, a more severe COVID-19 during the acute phase (higher CRP and longer hospitalization) was predictive of dyspnea during the follow-up period, as observed in previous studies." (PMID 37510773, 2023). "A significant increase in total serum Ferritin, PCT, CRP, and D-dimer was registered in COVID-19 deaths as compared to survivors." (PMID 38057707, 2023). "A meta-analysis evaluating laboratory indicators of COVID-19 found that nearly two-thirds of patients had elevated CRP." (PMID 37143167, 2023). "We also saw that CRP was significantly lower in the intervention group than in the control group, excluding mild COVID-19, suggesting that MSCs are a more suitable therapeutic method for severe COVID-19 patients." (PMID 37143167, 2023). "It was previously found that COVID-19 vaccination from both AstraZeneca and Pfizer can elevate CRP levels." (PMID 37626700, 2023). "Inconsistent with circulating EOS, the 3rd booster shot of COVID-19 vaccine demonstrated a more significant inhibitory effect on CRP." (PMID 37217986, 2023). "The CRP level correlates with CT findings and can predict severe COVID-19 because of its significant increase at the initial stage of the disease." (PMID 37720137, 2023). "Targher, Mantovani reported that the concentrations of C-reactive protein increased to 14.1 mg/L in diabetic patients infected with COVID-19, which suggested the activation of the monocyte–macrophage system, which is a central part of the cytokine storms." (PMID 37893490, 2023). "The results pointed out that infected COVID-19 individuals had an elevated range of CRP, LDH, and ferritin, which exhibited a marked increase in critical cases than in mild to moderate ones." (PMID 37754237, 2023). "Comparison of blood parameters on admission revealed higher white blood cell count, neutrophil count, urea and creatinine level, lactate dehydrogenase level, and C-reactive protein in patients with severe COVID-19." (PMID 36482706, 2023). "Serum levels of IL-23, IL-10, and TNF-α were significantly higher in COVID-19 patients with critical cases compared to mild and severe cases, and correlated positively with CRP level." (PMID 37283736, 2023).
COVID-19 (continued). "Among the variables with high ASMD are some natural COVID-19 parameters, such as CRP for inflammatory state, pulmonary ultrasound findings and findings in chest X-ray for lung function, and MEWS and SOFA, established warning scores for clinical deterioration." (PMID 37258639, 2023). "Consistent with another Swiss cohort of 145 COVID-19 patients with similar characteristics to our cohort, CRP was significantly higher in ventilated patients." (PMID 37596518, 2023). "CXR scores correlated with a few clinical variables, most notably with LDH, RR, D-dimer, and CRP, again indicating that CXRs are informative of COVID-19 disease severity." (PMID 36980414, 2023). "The most frequent manifestations in chagas-COVID-19 co-infected cases were increased blood troponin T, blood glucose alteration, low pO2, leukocytosis, and elevated CRP." (PMID 37091061, 2023). "In severe COVID-19 cases, leukocyte count, neutrophil/lymphocyte ratio, procalcitonin, CRP, and ferritin elevation are reported in the literature." (PMID 36681833, 2023). "In contrast, the impact of renal comorbidity on the mortality from COVID-19 has been well described, and the prognostic importance of CRP and BUN has been clearly reported as evident in multiple ML studies and meta-analyses." (PMID 36826535, 2023). "Here, our results confirm both the elevated CRP and white blood cell count findings as indicators of bacterial co-infection in COVID-19." (PMID 36691080, 2023). "In a meta-analysis of 56 studies involving 8719 patients with confirmed COVID-19, CRP was significantly higher in severe disease and in patients who died during follow-up." (PMID 37760914, 2023). "CRP was also measured objectively, and both were assessed before and after COVID-19, allowing for an assessment of changes from before to during COVID-19." (PMID 38136035, 2023). "The CRP, ferritin and d-dimer values of severe and critical cases were higher than those of mild COVID-19 cases." (PMID 37112613, 2023). "In severe/critical COVID-19 patients, IL-6, CRP, NLR, PLR, glucose, AST, urea, creatinine, and eGFR were significantly higher compared with the reference interval, while eosinophil count was significantly lower." (PMID 36838284, 2023). "Individuals with severe and fatal COVID-19 displayed neutrophilia and lymphopenia, as well as increased levels of CRP, ferritin, and cytokines such as IL-6, IL-10, gamma interferon (IFN-γ) and TNF-α." (PMID 36852984, 2023). "This study found a significant increase in the median serum level of CRP across all groups (P<0.000), with significantly higher values in individuals with bacterial pneumonia compared to COVID-19 (P<0.000) and the control group (P<0.000)." (PMID 38585537, 2023). "In the univariate analysis, by stratifying patients based on the combination of increasing or decreasing sPD-L1 levels, number of lymphocytes, and CRP levels, four prognostic groups of COVID-19 patients were identified based on their LOS." (PMID 37959277, 2023). "Studies have demonstrated that QT interval prolongation, a type of arrhythmia, is closely related to CRP levels in COVID-19 patients, and patients have higher CRP and WBC levels during hospitalization." (PMID 37575983, 2023). "For the laboratory/monitoring parameters, PE COVID-19 patients had higher CRP (OR 1.001 [1.0009–1.002]) and LDH values (1.0003 [1.00001–1.0006]); however, no appreciable clinical difference was noted, as the values were mostly overlapping." (PMID 36810085, 2023). "Previous studies have reported that white blood cells and C-reactive protein are early indicators of progression to serious disease and in-hospital mortality in COVID-19 patients." (PMID 36999038, 2023). "We identified a significant association between the increased value of ferritin (p < 0.0001, OR = 22.31), fibrinogen (p = 0.009, OR = 13.41), and C-reactive protein (p = 0.01, OR = 7.65) and the level of severity of COVID-19." (PMID 37623485, 2023).
COVID-19 (continued). "The network map and PCA plot showed that the closest neighbors of COVID-19 severity were ferritin and age, and CRP, scoring index of chest x-ray, albumin, and LDH were the next closest neighbors of these 3 factors." (PMID 36668902, 2023). "Previous evidence has shown that lymphocyte subsets significantly reduced, including CD3+T cells, CD4+T cells, and CD8+T cells, B cells, NK cells, and cytokine storms such as CRP are common in COVID-19 patients." (PMID 37799722, 2023). "Formerly active and active subjects, especially those who maintained usual levels of PA after COVID-19, showed lower BMI and C-reactive protein (CRP) levels, and higher vitamin D levels." (PMID 37048602, 2023). "Regarding biochemical parameters, median creatinine, MPV, and CRP were significantly higher in COVID-19 patients, whereas median eGFR, Na+, WBC, MCH, MCHC, and eosinophil percentages were significantly lower in this group." (PMID 36819137, 2023). "MASP-2 levels in hospitalized individuals with COVID-19 correlated with the inflammation marker C-reactive protein." (PMID 35816998, 2023). "We aimed to assess the importance of determining Ct value and SpO2 measurements upon admission in relation to regular laboratory markers (CRP and D-dimer), in order to predict COVID-19 mortality." (PMID 36999046, 2023). "CRP is a strong and early inflammatory marker, which is elevated in the serum of COVID-19 patients and a predictor of poor outcome." (PMID 38193087, 2023). "Patients with COVID-19 also had elevated neutrophil/lymphocyte ratios, neutrophil counts, and lactate dehydrogenase, C-reactive protein, D-dimer, and ferritin levels." (PMID 37493737, 2023). "In more than 70% of the COVID-19 intubated patients from the Roma ethnicity, there was a significant increase in C-reactive protein levels." (PMID 36836429, 2023). "In COVID-19 patients, CRP has been already described as a bad outcome predictor, together with the cytokines associated with its expression (IL-6, IL-10)." (PMID 37373750, 2023). "Of note, studies on other biomarker combinations, e.g., CRP and myxovirus resistance protein A, have shown promising results in regard to screening for COVID-19 and triaging in the emergency department (ED)." (PMID 36757525, 2023). "Analyzing the biomarkers within each study subgroup, we revealed that in mild COVID-19, only the CRP concentration was significantly increased, while in the other forms of COVID-19, all markers were significantly elevated (p < 0.05)." (PMID 37239895, 2023). "Our study is the first one that examined the correlation between PhA and ferritin and CRP concentrations in patients with COVID-19." (PMID 36986138, 2023). "Among patients with viral infection, CRP levels were highest in those with COVID-19 and lowest in those with viral exanthems." (PMID 37478118, 2023). "The ROC curve shows that high WBC counts and a high D-dimer are more sensitive predictive markers than CRP in the diagnosis of unstable severe COVID-19." (PMID 37235308, 2023). "Important independent factors associated with in-hospital mortality in elderly COVID-19 patients were age, sex, DNR status, diastolic blood pressure, body temperature, GCS score, total bilirubin, and CRP." (PMID 36814202, 2023). "In many studies, they reported that patients who died from COVID-19 had significantly higher levels of CRP, D-dimer, and procalcitonin than surviving patients, and they found that these parameters were associated with the mortality of the disease." (PMID 36919085, 2023). "For example, research has shown that transplant recipients had lower WHO severity scores and peak CRP levels upon COVID-19 admission." (PMID 38020145, 2023). "Our study reveals a positive correlation between serum CRP levels and circulating megakaryocyte proportion, suggesting an interaction between CRP and megakaryocytes in COVID-19." (PMID 38077346, 2023).